TPO (thyroid peroxidase)
Diseases named in the same sentence as TPO in open-access papers (continued):
Sharing a sentence is not in itself a finding about the gene and the disease.
hypothyroidism (continued). "The Whickham study demonstrated that the presence of antithyroid microsomal (TPO is the antigen involved in the “microsomal” response) antibodies, or elevated serum TSH alone, was associated with a significant increased risk of developing hypothyroidism at 20 years of age." (PMID 24592326, 2014). "Decreased availability of maternal thyroid hormone may also impair neurological development of the fetus as several studies have reported decreased IQ in infants born to mothers with either overt hypothyroidism (OH), hypothyroxinemia, or thyroid peroxidase antibody (TPO Ab) positivity." (PMID 23762776, 2013). "Mutations in ZnT10 result in thyroid-specific Mn2+ accumulation with inhibition of thyroid peroxidase (TPO), resulting in hypothyroidism." (PMID 41583444, 2025). "Moreover, in another meta-analysis, it was demonstrated that among pregnant women without overt thyroid disease, subclinical hypothyroidism, isolated hypothyroxinemia, and TPO antibody positivity were significantly associated with a higher risk of preterm birth." (PMID 40806900, 2025). "Autoantibodies to thyroid peroxidase (TPOAb) and thyroglobulin (TgAb) define preclinical autoimmune thyroid disease (AITD), which can progress to either clinical hypothyroidism or hyperthyroidism." (PMID 38996042, 2025). "Laboratory evaluation revealed biochemically severe hypothyroidism with elevated thyroid-stimulating hormone (TSH), low free thyroxine (FT4), and persistently high thyroid peroxidase antibodies (anti-TPO)." (PMID 40978905, 2025). "The comparison between the results of cases and controls in the literature for the variables hypothyroidism, positive anti-TPO, positive anti-TG and altered TSH showed a statistically significant difference for hypothyroidism." (PMID 37598033, 2024). "In more detail, three patients had positive anti-TPO and/or anti-Tg antibodies prior to ALZ initiation; of those, two were under treatment with levothyroxine due to hypothyroidism and one had toxic multinodular goiter (MNG) with subclinical hyperthyroidism." (PMID 36641771, 2023). "Antibodies of thyroid peroxidase (anti-TPO) and/or thyroglobulin (anti-TG) are increased, which serve as the main criteria for diagnosis if combined with symptoms of hypothyroidism or low echogenicity in ultrasound." (PMID 37090700, 2023). "The mean time to anti-TPO and/or anti-Tg antibody positivity onset (from first ALZ infusion) in patients with HT ± hypothyroidism was 19.2 ± 12.7 months (mean ± SD)." (PMID 36641771, 2023). "Newly diagnosed HT with hypothyroidism; TSH levels were above normal >10 mIU/L, and TPO and TG antibodies were positive." (PMID 37790207, 2023). "Although the increased incidence of hypothyroidism in the TPO Ab-positive group appears to develop early after RAI, the time of onset of hypothyroidism is comparable in both groups." (PMID 35687484, 2022). "Regarding treatment for DM, metformin has the effect of lowering TSH levels in DM patients with hypothyroidism or TSH levels in upper normal limits, or who are euthyroid and thyroid peroxidase antibody-positive." (PMID 36397244, 2022). "Complications pertain not only to overt hypothyroidism, but also SCH and the presence of circulating anti-thyroid peroxidase (anti-TPO) and anti-thyroglobulin (anti-TG) antibodies." (PMID 35329880, 2022). "Previous studies have also shown that the incidences of clinical hypothyroidism and SCH are significantly higher when subjects have high titers of TPO-Ab or test positive for both TG-Ab and TPO-Ab." (PMID 35242111, 2022). "His blood work was consistent with hypothyroidism, showing markedly elevated thyroid-stimulating hormone (TSH), suppressed T3 levels, and positive anti-thyroid peroxidase antibody titers." (PMID 34094769, 2021).
hypothyroidism (continued). "The inhibition of the TPO enzyme, which catalyses many steps of THs synthesis, leads to a reduced synthesis of THs that may in turn lead to a series of dysfunctions related to hypothyroidism, such as reduced basal metabolism and alteration in the lipidic assets." (PMID 34456728, 2021). "Autoimmune thyroiditis also occurs with a high frequency in DS; autoantibodies against the thyroid such as thyroid peroxidase (TPO) antibodies are present in almost one-third of those with DS, with a high likelihood of conversion to overt hypothyroidism." (PMID 34573243, 2021). "Previous studies demonstrated TAC correlated negatively with anti-TG and anti-TPO while TOS positively with anti-TG in euthyroid patients with AIT and HT patients developing overt hypothyroidism, which were consistent with our study." (PMID 32676110, 2020). "Moreover, patients positive for TPO-Ab and TG-Ab are more likely to develop hypothyroidism, and their concentrations can predict whether subclinical hypothyroidism will develop into clinical hypothyroidism." (PMID 32461982, 2020). "However, if adjusting for TPO-abs, the weak association between Tg-abs and hypothyroidism was not significant any more (p > 0.10), while if adjusting for Tg-abs, the association between TPO-abs and hyperthyroidism was still significant (p < 0.001, OR = 18.481, 95%CI = 4.510–75.739)." (PMID 31791284, 2019). "Anti-Thyroglobulin (ATG) was detected in 29% and Anti-thyroid peroxidase (ATPO) in 21% of the patients; of these children, 14% had hypothyroidism." (PMID 20444250, 2010). "Antibodies to thyroid peroxidase (TPO) were recorded in 40% (36/91) of the Turner women analyzed, and of these 50% had hypothyroidism." (PMID 18088406, 2007). "Indeed, this hypothesis may explain why some forms of mood disorders were associated with anti-TPO+ without hypothyroidism, as defined by blood routine tests." (PMID 16285879, 2005). "Indeed, this hypothesis may explain why some forms of mood disorders were associated with anti-TPO+ or thyroid autoimmunity without hypothyroidism, as defined by routine blood tests." (PMID 15317653, 2004). "The accumulation of oxygen free radicals may inhibit thyroid peroxidase (TPO) activity, thereby interfering with thyroid hormone production and contributing to the development of hypothyroidism." (PMID 40137541, 2025). "We have also seen that ferritin concentrations are decreased in anti-TPO negative hypothyroidism, but in the case of anti-TPO positive hypothyroidism, the ferritin concentrations are raised." (PMID 40937419, 2025). "Among those, 14 patients (17.7%) developed hypothyroidism, 7 of 38 (18.4%) who were anti-TPO positive and 7 of 41 (17.1%) who were anti-TPO negative (p=0.875)." (PMID 40255503, 2025). "Hypothyroidism after ATD occurred in 17.3% of patients with anti-TPO at diagnosis of GD compared to 20.8% without." (PMID 40255503, 2025). "Thyrotropin receptor antibodies measurements can help in the differential diagnosis of rapidly evolving hypothyroidism in women with negative TPO-Ab and thyrotropin receptor antibodies levels, especially in women of childbearing age." (PMID 40900474, 2025). "She had no past medical history but was later diagnosed with hypothyroidism with positive thyroid peroxidase (TPO) antibodies." (PMID 41450359, 2025). "Of note, some women with TS had neither hypothyroidism nor elevated TPO up to age 85 years with various karyotypes in the present national survey." (PMID 37758506, 2024). "In comparison to the control group, patients with scleroderma have a significantly higher likelihood of displaying anti-TPO antibodies with hypothyroidism (3.4-fold) and anti-TPO or/and anti-Tg without hypothyroidism (3.1-fold)." (PMID 38256549, 2024). "Among the nine patients who tested positive for TPOAb at baseline, 44% (4 out of 9) developed ICI-related hypothyroidism, compared to 2% (1 out of 44) in those who were TPO Ab negative at baseline." (PMID 38345684, 2024).
hypothyroidism (continued). "A slightly elevated TSH level associated with decreased free T4 and absence of thyroid peroxidase antibodies (TPO-Ab) suggested the development of secondary hypothyroidism." (PMID 39056048, 2024). "In the patient group, the Mean QoL was not significantly related to TSH-, FT4-, FT3- categories (low-in range-high), TPO Ab categories (negative-doubtful-positive), types of hypothyroidism, nor to most medication types (LT4 vs LT4 + LT3 and LT4 + DTE)." (PMID 38357535, 2024). "In comparison to the control group, patients with scleroderma had a significantly higher likelihood of displaying anti-TPO antibodies with hypothyroidism (3.4-fold) and anti-TPO or/and anti-Tg without hypothyroidism (3.1 fold)." (PMID 38256549, 2024). "Two independent researchers manually searched databases for the following keywords: “Turner syndrome”, “anti-TPO”, “anti-Tg”, “autoimmune thyroid disorders”, “TSH”, and “hypothyroidism”, which were entered into the search engine in isolation, as well as in combinations." (PMID 39684648, 2024). "The patient with prior hypothyroidism without positive anti-TPO/anti-Tg antibodies did not develop any autoimmunity and remained euthyroid under the initial treatment with levothyroxine." (PMID 36641771, 2023). "Other authors reported 20% CKD patients with hypothyroidism were TPO-Abs positive while 80% were negative and 74% of the control subjects were positive for TPO-Abs." (PMID 37623811, 2023). "One additional patient had hypothyroidism under treatment with levothyroxine without positive anti-TPO/anti-Tg antibodies." (PMID 36641771, 2023). "Similarly, in model 2, the odds of hypothyroidism was higher in the MUNW phenotype than in the MHNW phenotype after adjusting for the effects of age, sex, and TPO-Ab (OR=1.76; 95% CI=1.12, 2.79; P-value=0.015)." (PMID 36967773, 2023). "Patient A was also diagnosed with hyperthyroidism and secondary hypothyroidism with negative antibodies against thyroglobulin protein, thyroid peroxidase, and thyroxine receptor, indicating an autoinflammatory condition." (PMID 37273692, 2023). "We show that TPO Ab-positive patients were more likely to develop early hypothyroidism after the first administration of RAI, regardless of previously established factors associated with cure or treatment failure after RAI." (PMID 35687484, 2022). "The incidence of hypothyroidism was significantly higher in the TPO Ab-positive group compared to the TPO Ab-negative group in period 1 (89% vs 72%, P = 0.007) and period 2 (88% vs 72%; P = 0.019)." (PMID 35687484, 2022). "In period 1, 89% of the TPO Ab-positive group developed hypothyroidism and 72% in the TPO Ab-negative group (P = 0.007)." (PMID 35687484, 2022). "It thus appears that thyroid hormone system disruption by DE-71 does not result in the severe hypothyroidism and associated effects that can be ascribed to PTU and other potent TPO-inhibiting compounds." (PMID 35853081, 2022). "Epidemiological investigations have shown that in long-term follow-up, patients with positive anti-TPO and anti-Tg antibodies are more likely to develop hypothyroidism than are those who are negative." (PMID 36506504, 2022). "During DMF treatment, one female patient developed mild hypothyroidism with negative anti-TPO, anti-Tg and anti-TSHR autoantibodies; her serum TSH level then normalized spontaneously." (PMID 35624879, 2022). "Plasma thyroid peroxidase antibody (TPOAb) level was above the reference range in four (10%) patients, none of them having overt peripheral hypothyroidism." (PMID 34578397, 2021). "Once the autoantibodies (anti-TPO and antithyroglobulin) are positive, the etiology of hypothyroidism is defined, and there is no need to repeat them." (PMID 33587833, 2021). "Our study showed that patients can still develop hypothyroidism without the presence of anti-Tg and anti-TPO antibodies." (PMID 33299547, 2020).
hypothyroidism (continued). "Hypothyroidism was manifested by a persistent increase of thyroid stimulating hormone (TSH) first noted at 11 months old (with subsequently normal total and free thyroxine levels); his thyroid peroxidase antibodies were mildly positive." (PMID 31412917, 2019). "Following a pharmacological dose of soy phytoestrogens, there were no changes in thyroid function; however, two participants developed hypothyroidism after the high dose phytoestrogen phase, both of whom were TPO antibody negative." (PMID 30254609, 2018). "Autoimmune thyroiditis is confirmed by positive antithyroid antibodies (anti-TPO 85–90% higher) but its positivity does not imply hypothyroidism." (PMID 25436160, 2014). "The researchers highlighted that treatment led to a significant decrease in the anti-Tg and anti-TPO values of patients with hypothyroidism, while only a non-significant decrease was noted in those with subclinical hypothyroidism." (PMID 22155461, 2011). "Not recorded also, was the presence or absence of TPO autoantibodies in 30 of 46 patients with clinical hypothyroidism, 6 of 9 patients with sub-clinical and 34 of 47 with euthyroid Hashimoto's." (PMID 21172028, 2010). "Additionally, some authors have noted that CSU patients with anti-TPO antibodies are more likely to develop hypothyroidism or subclinical thyroid dysfunction, although there is no clear correlation between TSH levels and urticaria severity." (PMID 40075855, 2025). "Contrary to our hypothesis, anti-TPO at diagnosis did not correlate with an increased rate of hypothyroidism after ATD cessation." (PMID 40255503, 2025). "One female was diagnosed with hypothyroidism with anti TPO antibodies being negative." (PMID 40697385, 2025). "Our results seem to confirm these findings since the only infant treated with L-thyroxine for hypothyroidism was one of the 6% who never presented anti-TPO and anti-TG antibody positivity during the follow-up, and thus the hypothyroidism must be ascribed to other causes." (PMID 40128881, 2025). "Given the absence of TPO-Ab and TgAb, and the rapid evolution of hypothyroidism, a TRAb test was requested, which showed a positive result using a competitive electrochemiluminescence immunoassay (Roche Diagnostics Ltd., Basel, Switzerland; normal value <1IU/L), indicating an autoimmune etiology." (PMID 40900474, 2025). "Anti-TPO-negative individuals in the top 10% of the PRS distribution had a nearly twofold increased risk (hazard ratio (HR) = 1.97, 95% CI = 1.06–3.68, P = 0.033) of developing hypothyroidism compared to those in the bottom 90% of the distribution." (PMID 41238958, 2025). "This may indicate that anti-TPO could be an incidental marker of transient thyroid damage rather than a direct contributor to hypothyroidism development." (PMID 40255503, 2025). "However, given her TSH normalized weeks later and she had neither thyroglobulin antibodies nor thyroid peroxidase antibodies, this was thought to represent euthyroid sick syndrome rather than hypothyroidism." (PMID 38744309, 2024). "Of note the thyroid peroxidase Ab was done to show that the patient had Hashimoto’s thyroiditis rather than hypothyroidism secondary to an absence of thyroid gland or another unknown cause." (PMID 39618600, 2024). "Without anti-TPO data, it is challenging to determine whether cases of hypothyroidism are autoimmune in origin, which is relevant because autoimmune thyroid disease is often associated with PCOS and may influence thyroid management strategies." (PMID 40654392, 2024). "The criteria included subacute onset of cognitive impairment, psychiatric symptoms or seizures, euthyroid status or mild hypothyroidism, serum thyroid peroxidase antibodies (TPOAbs) > 200 IU/mL, absent neuronal antibodies in the serum/CSF and no other etiologies." (PMID 39000209, 2024).
hypothyroidism (continued). "Characteristics of healthy donors (CTR, control group) and patients with elevated TgAb and/or anti-TPO levels without symptoms of hypothyroidism (HT1), patients with Hashimoto’s thyroiditis (HT2) and patients with Graves’ disease before (GD) and after (GD/T) TSH normalization (study groups)." (PMID 35370997, 2022). "Interestingly, thyroid peroxidase antibody and thyroglobulin antibody have been evaluated in all cases with ScH and overt hypothyroidism, and both were negative." (PMID 36295508, 2022). "Despite no significant changes in subclinical hyperthyroidism or hypothyroidism or anti-thyroid peroxidase or anti-thyroglobulin antibody positivity prevalence, a significant increase in thyroid nodule prevalence (P < 0.0001) was found in the overall population." (PMID 34762596, 2021). "The absence of changes in the expression of NPY4R in patients with AIT-related hypothyroidism and a group of patients with rising serum autoantibodies suggests that the high level of serum autoantibodies, such as anti-Tg and anti-TPO, do not affect the expression of NPY4R." (PMID 34104248, 2021). "We assessed the number of subjects who had anti-TPO prior to the onset of subclinical/overt hypothyroidism and compared them to the control group (subjects with anti-TPO parallel, following, or never to the onset of subclinical/overt hypothyroidism)." (PMID 31467701, 2019). "In the remaining 17 cases of hypothyroidism, no measurement of TPO-Abs could be found." (PMID 38308768, 2024). "Subclinical hypothyroidism might increase the risk of postoperative complications within 90 days of TKA, especially for the patients with TSH ≥ 10 mu/L and positive anti‐TPO and those without corrected subclinical hypothyroid and thyroid hormone supplementation." (PMID 33817980, 2021). "111/152 (73.0%) subjects had anti-TPO prior to the onset of subclinical/overt hypothyroidism, 21/152 (13.8%) had anti-TPO parallel to the onset of subclinical/overt hypothyroidism, 1/152 (0.7%) had anti-TPO following the onset of subclinical/overt hypothyroidism, and 19/152 (12.5%) had no anti-TPO." (PMID 31467701, 2019). "Notably, unlike hypothyroidism, which presents with elevated TSH levels, decreased T4 and FT4 levels, and normal or decreased T3 and FT3 levels, usually caused by autoimmune thyroiditis with positive TPO antibodies, this condition features negative TPO antibodies." (PMID 40665986, 2025). "Development of hypothyroidism after discontinuation of ATD did not correlate with anti-TPO status at diagnosis (with anti-TPO: 17.3%; without anti-TPO: 20.8%)." (PMID 40255503, 2025). "In our study, three of the eight female students with elevated TPO-Ab (37.5%, 95% CI: 8.5%–75.5%) also had elevated TSH levels despite having no clinical features of hypothyroidism." (PMID 40927297, 2025). "In conclusion, our study showed that the presence of anti-TPO antibodies at GD diagnosis did not influence the relapse rate after ATD treatment, nor did it correlate with the development of hypothyroidism post-ATD." (PMID 40255503, 2025). "Among patients with anti-TPO and anti-TG antibodies, the group infected with HTLV-1 had a significantly greater proportion of biological hypothyroidism than the group that was not, but this observation was based on a small sample." (PMID 37293205, 2023). "In case of hypothyroidism, the time interval between RAI and initiation of L-T4 was similar in TPO Ab-positive patients compared to TPO Ab-negative patients (median, 60 days (Q1, 46 : Q3, 102) vs 76 days (Q1, 47 : Q3, 132); P = 0.193)." (PMID 35687484, 2022). "There is currently no consensus on the management of euthyroid (TSH ≤ 4 mIU/L), anti-TPO positive women; however, if hormone treatment is not started, it is advised to monitor TSH levels closely during pregnancy for the development of hypothyroidism." (PMID 33874925, 2021).